IL13 (interleukin 13)
Diseases named in the same sentence as IL13 in open-access papers (continued):
Sharing a sentence is not in itself a finding about the gene and the disease.
infectious disease (13 papers, 2011 to 2026). A disorder directly resulting from the presence and activity of a microbial, viral, or parasitic agent in humans. "Previous studies associated interleukin (IL)-13 with pathogenesis of different infectious diseases, including P. falciparum malaria." (PMID 23521898, 2013). "IL-13 has been shown to be associated with the severity of several infectious diseases." (PMID 37041520, 2023). "ARG1 is expressed by macrophages, and downregulates immunosuppressive cytokine production (e.g., IL-4, IL-5, and IL-13) by T-helper cell 2 (Th2) in response to infectious disease." (PMID 35008799, 2021). "Another candidate, IL4R, encoding the alpha chain of the interleukin-4 receptor that can bind IL4 and IL13, has not been previously reported to be associated with infectious diseases." (PMID 37033939, 2023). "Since IL-13 signaling and its unique receptor IL-13Rα2 contribute to the prolongation of inflammation in various infectious diseases, this study might be useful in seeking potential therapeutic targets to prevent Th2 cytokine-related diseases." (PMID 31010051, 2019).
cardiovascular disease (10 papers, 2021 to 2025). "Overall, the study of IL-13 gene polymorphism holds promise for enhancing risk assessment, prognosis prediction, and therapeutic interventions in the context of MI and cardiovascular disease management." (PMID 39088580, 2024). "Functional variations in the IL13 gene have been linked with different types of cardiovascular diseases." (PMID 39088580, 2024). "In cardiovascular disease, pathological and protective roles are reported for the Th2 cytokines IL-4 and IL-13, respectively." (PMID 37949903, 2023). "The present study has the potential to inform on more selective targeting of IL-4 and IL-13 and their downstream effector molecules in cardiovascular disease." (PMID 37949903, 2023). "Although IL-13 shows great therapeutic potential in the treatment of cardiovascular diseases, the role of IL-13 in protecting the septic cardiomyopathy remains to be further understood." (PMID 34616745, 2021). "Taken together, these findings suggest that despite both promoting a M2 phenotype, IL-4 and IL-13 may play opposing roles in cardiovascular disease." (PMID 37949903, 2023). "The similar actions of IL-4 and IL-13 on M1 and M2 macrophages suggests that the opposing roles of these cytokines in cardiovascular disease may be via effects on other cell types." (PMID 37949903, 2023). "Given the central inflammatory role that macrophages play in cardiovascular disease, we hypothesised that the opposing effects of IL-4 and IL-13 may be via their differential modulation of M2 macrophage function, specifically the release of ROS." (PMID 37949903, 2023). "With this in mind, we wished to determine whether NOX2-derived ROS may be more prevalent in M2 macrophages polarised with IL-4, as compared to IL-13 and thus, be involved in the potentially opposing roles of these cytokines in cardiovascular disease." (PMID 37949903, 2023). "Future studies should focus on a direct comparison of IL-4 and IL-13 as well as their cytokine-specific receptor subunits (i.e., IL-2Rγ and IL-13Rα1, respectively) in the context of cardiovascular disease in vivo to validate the therapeutic potential of targeting one cytokine over the other." (PMID 37949903, 2023). "Hence some of the protective actions of IL-13 in cardiovascular disease could be mediated via the IL-13Rα2 receptor, leading to increased collagen deposition and plaque stability, or reparative connective tissue formation following MI." (PMID 37949903, 2023). "With the capacity to activate both the type I and type II IL-4 receptor, leading to downstream signalling associated with enhanced NADPH oxidase activity, IL-4 may serve as a greater stimulus for macrophage ROS generation than IL-13 in the setting of cardiovascular disease." (PMID 37949903, 2023). "Overall, this study did not identify major differences in the ability of IL-4 and IL-13 to modulate macrophage function, suggesting that the opposing roles of these cytokines in cardiovascular disease are likely to be via actions on other cell types." (PMID 37949903, 2023). "There wasno statistically significant difference between IL-8, IL-10, IL-13, TGF-1,in CKD patients with and without cardiovascular disease (p> 0.05)." (PMID 33711092, 2021).
neurodegenerative disease (10 papers, 2017 to 2025). A disorder of the central nervous system characterized by gradual and progressive loss of neural tissue and neurologic function. "It seems that the role of IL-13, even within different neurodegenerative diseases, induces different effects, and the reasons remain elusive." (PMID 34489558, 2021). "Individually, IL-5 and IL-13 have been shown to modulate neuroinflammation in neurodegenerative diseases." (PMID 34489558, 2021). "HBOT increased the production of IL-4 and IL-13 to exert the anti-inflammatory effects in spinal cord injury and neurodegenerative diseases, respectively." (PMID 34440146, 2021). "It was previously found that the IL-4 and IL-13 signaling pathways play a neuromodulating role by regulating the oxidative stress in AD and other neurodegenerative diseases." (PMID 32382304, 2020). "The potent immunomodulatory effect of IL13 encourages to further evaluate the application of this cytokine in clinically relevant neurodegenerative disease models." (PMID 29866203, 2018). "These pathways were, in general, shared across all neurodegenerative diseases, even though the major overlap was found for the synaptic functions (BDNF, CCL2, ACHE, GFAP, NEFH or NEFL) and microglia pathways (TREM2, IL13, IL6R IFNG)." (PMID 41250190, 2025).
lung (7 papers, 2014 to 2026). "In turn, IL-4/IL-13-induced AAM upregulate Ear11 production and inducing IL-25-dependent lung neutrophilia." (PMID 32457448, 2021).
metabolic disease (7 papers, 2018 to 2024). A congenital disorder (due to inherited enzyme abnormality) or acquired (due to failure of a metabolically important organ) disorder resulting from an abnormal metabolic process. "The results showed that decreased metabolic disorder in recipient mice was accompanied by a significant elevation of Th2-type cytokines, including IL-4, IL-5, IL-6, IL-10, and IL-13." (PMID 38195424, 2024). "However, there are only a few publications on the effect of IL-13 on metabolic diseases and possible therapies to influence them." (PMID 37629063, 2023). "However, clinical findings in humans regarding the role of IL-13 in metabolic disease are still controversial." (PMID 29675435, 2018).
adenocarcinoma (5 papers, 2017 to 2025). A common cancer characterized by the presence of malignant glandular cells. "Recently, we have linked the expression of galectin-3 on the A549 epithelial cell line –an adenocarcinoma, to the activation of human basophils for the release of histamine and secretion of IL-4 and IL-13." (PMID 33154744, 2020). "Notably, studies using the transgenic adenocarcinoma of the mouse prostate (TRAMP) model have demonstrated that IL-13 plays a role in prostate tumorigenesis." (PMID 40247153, 2025). "However, we recently reported evidence for a unique mode of IgE-dependent activation in basophils whereby these granulocytes released histamine and secreted large quantities of IL-4/IL-13 when co-cultured with the A549 epithelial cell (EC) line –an adenocarcinoma of lung origin." (PMID 33154744, 2020).
neurological diseases (5 papers, 2013 to 2024). "Likewise, in humans, IL13 expression has shown to be associated with the development of neurological disorders, and with the experience of more severe neuropsychiatric symptoms." (PMID 36195636, 2022).
hematological malignancies (4 papers, 2017 to 2022). "The prognostic value of serum IL-13 level has been evaluated previously in other hematological malignancies." (PMID 35011853, 2021). "This suggests the possibility that CACNA1B could have unrecognized effects on the immune system by disrupting IL-13 and Th17 signaling leading to PANS and an increased risk of hematological malignancy." (PMID 35773312, 2022).
psychiatric disorder (3 papers, 2021 to 2025). A disorder characterized by behavioral and/or psychological abnormalities, often accompanied by physical symptoms. "In contrast with the common inflammatory hypothesis in psychiatric disorders, this study found downregulation of several pro-inflammatory cytokines in patients, including IL-8, IL-12, and IL-13." (PMID 40650038, 2025).
benign tumors (2 papers, 2018 to 2020). "The IL13Rα2 expression level is lower in these benign tumors than that of the MPNSTs, but it is still present in detectable amounts, suggesting the opportunity to target those benign tumors with IL13 conjugated liposomes for efficacious therapy." (PMID 29304038, 2018).
cardiac disease (2 papers, 2017 to 2022). "As conclusion, a gene‐therapy approach to re‐express GATA4 or protein therapy with IL‐13 might be evaluated as therapeutic strategies to enhance myocardial regeneration in pediatric patients with heart disease or even in adult patients after MI in the future." (PMID 28053183, 2017). "If this is the case, enhancement of cardiac GATA4 levels or administration of IL‐13 might be evaluated as therapeutic strategy to improve myocardial regeneration in heart disease." (PMID 28053183, 2017).
peripheral neuropathy (2 papers, 2024 to 2025). A disorder affecting the peripheral nervous system. "Furthermore, paclitaxel-exposed T cells stimulate macrophages to secrete interleukin-10 (IL-10) via interleukin-13 (IL-13), and macrophage-derived IL-10 engages IL-10 receptors (IL-10R) on DRGs to counteract paclitaxel-induced peripheral neuropathy." (PMID 41229440, 2025). "Studies in mice have shown that IL-13 released from T cells can polarize macrophages into an M2-like phenotype, and the resulting production of anti-inflammatory cytokines from these polarized macrophages was found to be critical for the resolution of chemotherapy-induced peripheral neuropathy.." (PMID 38585987, 2024).
central nervous system disorder (1 paper, 2022). A disease involving the central nervous system. "Previous studies have shown that IL-13 signals were through the IL-13 Rα1 and activated JAK/STAT pathway, mediating inflammatory responses and cell survival in central nervous system disorders." (PMID 35757105, 2022).
head and neck tumor (1 paper, 2013). "Mice treated with IL-13-PE continued to gain weight while the controls lost weight due to the developing head and neck tumors (P value < 0.0001)." (PMID 23421960, 2013). "Other treatment delivery options for IL-13-PE could improve the effectiveness of this immunotoxin in the Tgfbr1/Pten 2cKO mice such as direct injection into the head and neck tumors or a surgically implanted continuous infusion pump." (PMID 23421960, 2013).
hematologic cancer (1 paper, 2022). "The Severe-Death hematologic cancer group also had elevated concentrations of IL-5 and IL-13." (PMID 36700209, 2022).
IL13 also shares sentences with these, for which no sentence is quoted: chronic periodontitis (5 papers); chronic kidney disease (4); chronic sinusitis (4); eosinophilic granulomatosis with polyangiitis (4); Non-Alcoholic Steatohepatitis (4); portal hypertension (4); biliary atresia (3); idiopathic nephrotic syndrome (3); intestinal inflammation (3); measles (3); myeloproliferative disease (3); renal carcinoma (3); acute myocardial infarction (2); adenoma (2); adrenocortical carcinoma (2); autoimmune hypothyroidism (2); babesiosis (2); basophilic leukemia (2); bronchitis (2); cholangiocarcinoma (2); combined immunodeficiency (2); dilated cardiomyopathy (2); diphtheria (2); esophageal disease (2); esophageal squamous cell carcinoma (2); gallstones (2); hypereosinophilic syndrome (2); insomnia (2); Schistosomiasis japonica (2); Schistosomiasis mansoni (2).
A further 156 diseases each share a sentence with IL13 in 2 papers or fewer.